H3-3A (H3.3 histone A)
Description:
Variant histone H3 which replaces conventional H3 in a wide range of nucleosomes in active genes. Constitutes the predominant form of histone H3 in non-dividing cells and is incorporated into chromatin independently of DNA synthesis. Deposited at sites of nucleosomal displacement throughout transcribed genes, suggesting that it represents an epigenetic imprint of transcriptionally active chromatin. Nucleosomes wrap and compact DNA into chromatin, limiting DNA accessibility to the cellular machineries which require DNA as a template. Histones thereby play a central role in transcription regulation, DNA repair, DNA replication and chromosomal stability. DNA accessibility is regulated via a complex set of post-translational modifications of histones, also called histone code, and nucleosome remodeling.
Synonyms: H3.3A; H3F3; H3F3A; BRYLIB1
Gene: Protein-coding gene on chromosome 1 (226,061,571 to 226,073,206, forward strand). Ensembl gene ENSG00000163041.
Subcellular location: Nucleus; Chromosome
Subcellular location (Human Protein Atlas): Nucleoplasm
Pathways (Reactome):
Gene expression (Transcription): B-WICH complex positively regulates rRNA expression; DNA methylation; ERCC6 (CSB) and EHMT2 (G9a) positively regulate rRNA expression; MLL4 and MLL3 complexes regulate expression of PPARG target genes in adipogenesis and hepatic steatosis; NoRC negatively regulates rRNA expression; PRC2 methylates histones and DNA; RNA Polymerase I Promoter Escape; RNA Polymerase I Promoter Opening; RUNX1 regulates genes involved in megakaryocyte differentiation and platelet function; RUNX1 regulates transcription of genes involved in differentiation of HSCs; Regulation of endogenous retroelements by KRAB-ZFP proteins; Regulation of endogenous retroelements by Piwi-interacting RNAs (piRNAs); Regulation of endogenous retroelements by the Human Silencing Hub (HUSH) complex; SIRT1 negatively regulates rRNA expression; Transcriptional regulation by small RNAs
Chromatin organization: CHD1 and CHD2 subfamily; CHD6, CHD7, CHD8, CHD9 subfamily; Interaction of NuRD complexes with transcription factors; NuRD complex assembly
Developmental Biology: Activation of anterior HOX genes in hindbrain development during early embryogenesis; Chromatin modifications during the maternal to zygotic transition (MZT); Replacement of protamines by nucleosomes in the male pronucleus; Transcriptional regulation of granulopoiesis
Signal Transduction: Activated PKN1 stimulates transcription of AR (androgen receptor) regulated genes KLK2 and KLK3; Estrogen-dependent gene expression; Formation of the beta-catenin:TCF transactivating complex; Pre-NOTCH Transcription and Translation
Cell Cycle: Condensation of Prophase Chromosomes; Inhibition of DNA recombination at telomere
Cellular responses to stimuli: Oxidative Stress Induced Senescence; Senescence-Associated Secretory Phenotype (SASP)
Immune System: FXIIa activates plasma kallikrein-kinin system; Regulation of PD-L1(CD274) transcription
Cell-Cell communication: Negative Regulation of CDH1 Gene Transcription
DNA Replication: Assembly of the ORC complex at the origin of replication
Disease: Defective pyroptosis
Hemostasis: Factors involved in megakaryocyte development and platelet production
Metabolism of proteins: Amyloid fiber formation
Reproduction: Meiotic recombination
Gene Ontology:
Molecular function: nucleosomal DNA binding; protein binding; RNA polymerase II cis-regulatory region sequence-specific DNA binding; RNA polymerase II core promoter sequence-specific DNA binding; structural constituent of chromatin; DNA binding; protein heterodimerization activity
Biological process: nucleosome assembly; positive regulation of cell growth; heterochromatin formation; kinetochore assembly; mitotic metaphase chromosome alignment; telomere organization
Cellular component: chromosome; chromosome, telomeric region; extracellular exosome; nucleoplasm; nucleosome; nucleus; protein-containing complex; extracellular region; kinetochore
Gene-disease validity (ClinGen):
ClinGen rates the evidence that H3-3A causes each of these diseases.
Bryant-Li-Bhoj neurodevelopmental syndrome 1 (autosomal dominant): Definitive.
Homologues: Orthologues: guinea pig H3-5 (100% identical), macaque H3-3A (100% identical), Caenorhabditis elegans his-71 (99% identical). Paralogues in human: H3-3B (100% identical), H3C13 (97% identical), H3C14 (97% identical), H3C15 (97% identical), H3C1 (96% identical), H3C10 (96% identical), H3C11 (96% identical), H3C12 (96% identical), H3C2 (96% identical), H3C3 (96% identical), H3C4 (96% identical), H3C6 (96% identical), and 8 more.
Diseases named in the same sentence as H3-3A in open-access papers:
H3-3A is named in the same sentence as 24 diseases in open-access papers, as found by Europe PMC text mining. Sharing a sentence is not in itself a finding about the gene and the disease. The quoted sentences say what the papers report.
glioma (8 papers, 2016 to 2026). A benign or malignant brain and spinal cord tumor that arises from glial cells (astrocytes, oligodendrocytes, ependymal cells). "PURPOSE: The prognosis for pediatric high-grade gliomas associated with mutations in the H3-3A gene is very poor." (PMID 41925941, 2026).
tumor (4 papers, 2022 to 2025). "Direct sequencing of the H3-3A gene revealed a p.Gly35 mutation in all tumours from the GCTB group." (PMID 35055156, 2022). "Furthermore, mutations in the IDH1 gene, as well as depletion of histone chaperone ASF1, have been implicated in the activation of the ALT phenotype, indicating that ALT activation in tumor cells is not solely dependent on ATRX/H3-3A mutations." (PMID 37370681, 2023).
cancer (3 papers, 2021 to 2024). A tumor composed of atypical neoplastic, often pleomorphic cells that invade other tissues. "Next, we investigated why certain histone genes (e.g., H3-3A) were highly mutated across cancers while other genes harboring the same or similar protein sequences were rarely mutated." (PMID 37640703, 2023).
H3-3A also shares sentences with these, for which no sentence is quoted: Alpha-thalassemia (1 paper); alpha-thalassemia/mental retardation syndrome X-linked (1); amyotrophic lateral sclerosis (1); bone tumours (1); Congenital cataracts (1); COVID-19 (1); developmental delay (1); diffuse intrinsic pontine glioma (1); diffuse midline glioma (1); Giant Cell Tumour (1); glioblastoma (1); Infertility (1); insulinomas (1); mental retardation syndrome X-linked (1); Neurodevelopmental delay (1); neurodevelopmental disorder (1); neuropathy (1); oral cancer (1); pulmonary atresia (1); spinal astrocytomas (1); thalassemia (1).